SLC25A47 (solute carrier family 25 member 47)
Description:
Mitochondrial NAD(+) transporter that acts as a 'metabolic gate' in hepatic lipogenesis. Provides NAD(+) substrate to mitochondrial SIRT3 deacetylase and enables its NAD(+)-dependent activities in mitochondrial energy metabolism. This triggers downstream activation of PRKAA1/AMPK-alpha signaling cascade that negatively regulates sterol regulatory element-binding protein (SREBP) transcriptional activities and ATP-consuming lipogenesis to restore cellular energy balance. May transport other mitochondrial metabolites having an aromatic nucleotide and phosphate groups, such as acetyl-CoA. Does not transport amino acids. The transport mechanism remains to be elucidated.
Synonyms: C14orf68; HDMCP; HMFN1655; HDCMP
Tractability: Antibody: UniProt predicts a signal peptide or a membrane-spanning region.
Gene: Protein-coding gene on chromosome 14 (100,323,339 to 100,330,421, forward strand). Ensembl gene ENSG00000140107.
Subcellular location: Mitochondrion inner membrane; Mitochondrion outer membrane
Gene Ontology:
Molecular function: acetyl-CoA transmembrane transporter activity; NAD transmembrane transporter activity
Biological process: acetyl-CoA transport; NAD transmembrane transport; transmembrane transport
Cellular component: mitochondrial inner membrane; mitochondrion; mitochondrial outer membrane
Genetic constraint (gnomAD): Loss-of-function variants: 36 observed, 32.97 expected, observed/expected ratio (o/e) 1.09, 90% interval 0.84 to 1.44. The upper end of that interval is the gene's LOEUF score, 1.44, which puts it in group 5 of 6, group 1 being the genes least tolerant of losing a copy. Missense variants: 430 observed, 435.43 expected, observed/expected ratio (o/e) 0.99, 90% interval 0.91 to 1.07. Synonymous variants: 204 observed, 194.76 expected, observed/expected ratio (o/e) 1.05, 90% interval 0.93 to 1.18.
Homologues: Orthologues: chimpanzee SLC25A47 (98% identical), macaque SLC25A47 (94% identical), pig SLC25A47 (88% identical), mouse Slc25a47 (88% identical), dog SLC25A47 (87% identical), rabbit SLC25A47 (85% identical), rat Slc25a47 (85% identical), guinea pig SLC25A47 (81% identical), tropical clawed frog slc25a47 (57% identical), zebrafish slc25a47a (51% identical), zebrafish slc25a47b (34% identical). Paralogues in human: SLC25A45 (41% identical), SLC25A48 (40% identical), SLC25A29 (36% identical), SLC25A20 (33% identical), SLC25A12 (28% identical), SLC25A13 (28% identical), SLC25A34 (28% identical), UCP3 (27% identical), SLC25A2 (26% identical), SLC25A15 (26% identical), SLC25A22 (26% identical), SLC25A1 (25% identical), and 37 more.
Diseases named in the same sentence as SLC25A47 in open-access papers:
SLC25A47 is named in the same sentence as 13 diseases in open-access papers, as found by Europe PMC text mining. Sharing a sentence is not in itself a finding about the gene and the disease. The quoted sentences say what the papers report.
hepatoma (2 papers, 2025). "Quantitative PCR confirmed the induction of SLC25A47 mRNA by PPARα activation in human hepatocytes, human liver slices, and human hepatoma HepG2 cells." (PMID 39746607, 2025). "In addition, Slc25a47 expression was significantly induced by PPARα activation in mouse hepatocytes, rat FAO hepatoma cells, and mouse liver." (PMID 39746607, 2025). "In HepG2 human hepatoma cells that have endogenous SLC25A47, the mitochondrial NAD+ content was similarly unaltered by SLC25A47 overexpression and consistently decreased by the silencing of SLC25A51 but not SLC25A47." (PMID 41266821, 2025).
liver fibrosis (2 papers, 2023 to 2025). "In contrast, a recent study showed that genetic loss of Slc25a47 led to mitochondrial dysfunction, mitochondrial stress, and liver fibrosis in mice." (PMID 36812201, 2023). "However, our data showed that acute depletion of SLC25A47 by ~50% sufficiently restricted gluconeogenesis and enhanced insulin tolerance in adult mice without causing liver fibrosis and mitochondrial dysfunction." (PMID 36812201, 2023). "Our data do not confirm previously suggested roles of SLC25A47 in uncoupling, energy expenditure, lipid synthesis, fatty acid oxidation, liver fibrosis, mitochondrial stress, NAD+ transport, and gluconeogenesis." (PMID 39746607, 2025). "Furthermore, acute SLC25A47 depletion did not alter the expression of liver fibrosis marker genes." (PMID 36812201, 2023).
Hepatic steatosis (1 paper, 2023). Steatosis is a term used to denote lipid accumulation within hepatocytes. "In yeast, SLC25A47 overexpression elevated mitochondrial electron transport chain uncoupling, implicating its protective role against hepatic steatosis." (PMID 36812201, 2023). "This tissue specificity makes SLC25A47 an attractive therapeutic target, considering the recent successful examples in which liver-targeting mitochondrial uncouplers protected mice against type 1 and type 2 diabetes, hepatic steatosis, and cardiovascular complications (47, –49)." (PMID 36812201, 2023).
Hyperglycemia (1 paper, 2023). An increased concentration of glucose in the blood. "The present work showed that depletion of SLC25A47 reduced mitochondrial pyruvate flux, thereby restricting lactate-derived hepatic gluconeogenesis and preventing hyperglycemia." (PMID 36812201, 2023). "With these results in mind, we consider that SLC25A47 is a plausible target for hyperglycemia and type 2 diabetes for the following reasons." (PMID 36812201, 2023).
Insulin resistance (1 paper, 2025). Increased resistance towards insulin, that is, diminished effectiveness of insulin in reducing blood glucose levels. "To examine the possible metabolic consequences of SLC25A47 deficiency, we placed the wild-type and Slc25a47−/− mice on a HFD for 20 weeks to induce obesity and insulin resistance." (PMID 39746607, 2025).
Obesity (1 paper, 2025). Accumulation of substantial excess body fat. "We first studied the effects of Slc25a47 overexpression under conditions of obesity and fatty liver." (PMID 39746607, 2025).
Type 2 Diabetes (1 paper, 2023). "Another important observation is in human genetic association studies from the Type 2 Diabetes Knowledge Portal (type2diabetesgenetics.org), wherein we found significant associations between SLC25A47 and glycemic and lipid homeostasis." (PMID 36812201, 2023).
cancer (1 paper, 2025). A tumor composed of atypical neoplastic, often pleomorphic cells that invade other tissues. "To further investigate the potential role of SLC25A47 as a mitochondrial uncoupler, we performed studies in Hepa 1–6 cells, which do not express Slc25a47, nor do any other cancer cell lines part of the Cancer Cell Line Encyclopedia." (PMID 39746607, 2025).
infection (1 paper, 2023). The state of being infected such as from the introduction of a foreign agent such as serum, vaccine, antigenic substance or organism. "We found three genes that were commonly activated with infection with SCV2 at both 12 and 24 hpi (DUSP1, HES1, KLF2) and some non-congruent genes at 12 hpi (CCL5, ZBP1, NRXN2, STAB1, SLC25A47, CXCL11) and 24 hpi (FOXA2, RHOB)." (PMID 37504520, 2023).
SLC25A47 also shares sentences with these, for which no sentence is quoted: metabolic disease (1 paper); nonalcoholic steatohepatitis (1); steatosis (1); thyroid carcinoma (1).